EGFR (epidermal growth factor receptor)
Diseases named in the same sentence as EGFR in open-access papers (continued):
Sharing a sentence is not in itself a finding about the gene and the disease.
liver cancer (continued). "Disease-related types include epidermal growth factor receptor (EGFR) for cancer, Ataxia telangiectasia mutated (ATM) for Ataxia telangiectasia and Androgen receptor (AR) for liver cancer conserved in both mammals and fish." (PMID 25520927, 2014). "A link between TGF/EGFR/NOX signaling has emerged as a mechanism that dictates cell death or apoptotic cell resistance in liver cancer cells." (PMID 23434665, 2013). "The upregulation of uPA and uPAR expression in HCC, and its relationship with the invasiveness, metastasis, and prognosis of HCC suggest a possible role of the uPAR-integrin-EGFR-multiprotein complex in liver cancer." (PMID 24212818, 2011). "In liver cancer, multiple different groups’ investigations showed that METTL14 inhibits EMT, invasion and metastasis of liver cancer cells by regulating m6A-modified target mRNAs such as EGFR/PI3K/AKT, DGCR8/primiR-126, USP48/SIRT6/glycolysis, CSAD, GOT2 and SOCS2." (PMID 40734692, 2025). "Accordingly, combined treatment with the EGFR inhibitor gefitinib and lenvatinib exerts strong anti-proliferative effects in EGFR-expressing liver cancer cell lines in vitro, as well as in xenografted cell lines, immunocompetent mouse models, and patient-derived HCC xenografts in vivo." (PMID 41155983, 2025). "Moreover, it can reduce angiogenesis through the downregulation of vascular endothelial growth factor and its receptors, and delay cell growth by obstructing the EGFR/AKT/protein kinase B/GSK3 signaling pathway in liver cancer (Huh7 and Hep G2) cells." (PMID 40490812, 2025). "EGFR is a crucial regulator of angiogenesis, primarily involved in the maturation of neovascularization and the initiation of tumor angiogenesis, which is closely related to the proliferation of blood vessels in liver cancer." (PMID 39598341, 2024). "Additionally, oxymatrine was shown to regulate the expression of EGFR, a core therapeutic target, contributing to its efficacy in treating liver cancer." (PMID 39457402, 2024). "Western blot results showed that oxymatrine could reduce the expression of p-EGFR in HepG2 cells and achieve a therapeutic effect on liver cancer." (PMID 39457402, 2024). "MiR-206, for example, decreases EGFR expression to limit the formation of liver cancer stem cells." (PMID 37965067, 2023). "The possibility of the physical interaction between RNF12 and EGFR might lay a foundation to develop intervention strategies for liver cancer prevention and therapy." (PMID 37132043, 2023). "Other evidence supports a key role for EGFR signaling in different types of liver cancer." (PMID 38138981, 2023). "Whether RNF12 could activate EGF/EGFR signalling by interacting with EGFR to promote the progression of liver cancer was therefore a pertinent question." (PMID 37132043, 2023). "In addition, there was one experiment show that inhibition of epidermal growth factor receptor (EGFR) is synthetic lethal with lenvatinib in liver cancer." (PMID 36891274, 2023). "In particular, the up-regulation effect of fisetin on EGFR expression was stronger in liver cancer cells (HepG2), and the RNA expression was increased by about 10 times, while the expression of EGFR in normal liver cells (L02) was only increased by 3.6-fold under fisetin stimulation." (PMID 37996895, 2023). "•EGFR hyperactivation as a new target in poor-prognosis liver cancer." (PMID 38154692, 2023). "Notably, DeepRescore2-processed data uniquely identifies EGFR hyperactivation as a new target in poor-prognosis liver cancer, which is validated experimentally." (PMID 38154692, 2023). "Additionally, confocal immunofluorescence microscopy was used to assess the co‐localization of RNF12 and EGFR in liver cancer cell lines." (PMID 37132043, 2023).
liver cancer (continued). "The combination of EGFR inhibitors gefitinib and lenvatinib shows effective anti-proliferation effects in EGFR-expressing liver cancer cell lines, mouse liver cancer xenograft tumor models, genetically engineered mouse orthotopic liver cancer models, and PDX liver cancer models." (PMID 35189910, 2022). "EGFR plays a complex role in liver cancer where it is typically upregulated." (PMID 35379333, 2022). "Agents targeting epidermal growth factor receptor (EGFR), mainly including tyrosine kinase inhibitors (TKIs), such as sorafenib or lenvatinib, have been approved as first-line drugs for the treatment of advanced liver cancer." (PMID 35433466, 2022). "According to above results, the DDX20 may be a potential predicted biomarker and EGFR target gene for liver cancer." (PMID 36246406, 2022). "In liver cancer, EGFR activates hepatocyte growth factor (HGF) expression by repressing miR-26a/b expression, and the upregulation of paracrine HGF, which binds to the c-MET receptor of migrated cancer cells, promotes the proliferation of metastatic cancer cells." (PMID 33909822, 2021). "This may in turn promote liver cancer cell growth through activation of EGFR and the ensuing MAPK/ERK signaling." (PMID 33925807, 2021). "Because liver cancer arises from chronic liver damage, EGFR signaling may be needed for the maintenance of liver function." (PMID 33806040, 2021). "Following with experimental verification, the identified genes of ESR1, EGFR may function as potential screening anti-liver cancer markers." (PMID 34592904, 2021). "Exploring the underlying reasons, they noticed although both sorafenib and lenvatinib are multi-TKIs, only lenvatinib inhibits FGFR signaling which is essential for the combination therapy, and the combination of FGFR inhibitor and EGFR inhibitor had similar synergistic effects against liver cancer." (PMID 34608130, 2021). "Moreover, treatment with metformin can increase sorafenib sensitivity through AMPK activation in EGFR-overexpressed liver cancer cells." (PMID 33681180, 2021). "Additionally, the addition of delphinidin (a flavonoid) and ginsenoside Rg3 to the culture medium inhibited the EGFR/Akt/ERK signal axis in liver cancer cells." (PMID 34572344, 2021). "We also chose different liver cancer cell lines to test whether their sensitivities to cinobufagin are related to EGFR status." (PMID 34925034, 2021). "We showed that silencing HBXIP or EGFR could also inhibit the migration of HepG2 cells, which suggests that the other target genes of miR-520b also contribute to the migration of liver cancer cells except MLK3." (PMID 32214367, 2020). "A previous study indicates that there is an increment of serum EGFR level in liver cancer patients." (PMID 32256653, 2020). "In addition, catechol suppressed EMT-related steps such as migration, invasion, anoikis resistance acquisition, and stem cell-like characterization through the EGFR-AKT-ERK signaling pathway during liver cancer metastasis." (PMID 32376896, 2020). "In contrast, some studies have shown that YTHDF2 could inhibit the progression of liver cancer by stabilizing EGFR or IL-11 mRNA." (PMID 33519919, 2020). "Moreover, we identified miRNA-mediated deregulation of several other cancer-related biological processes, including angiogenesis, apoptosis, epidermal growth factor receptor (EGFR)/ErbB signaling, and insulin signaling in gastric, colorectal or liver cancers." (PMID 29459716, 2018). "Studies carried out on liver cancer have shown that chronic tissue damage and inflammation in liver result in a sustained overexpression and overstimulation of the EGFR pathway and that the deregulated EGFR signaling has been reported to play an important role in the development of liver cancer." (PMID 30627539, 2018). "EGF and EGFR were overexpressed in many cancers, such as breast, lung and liver cancer 17,20,21." (PMID 24268047, 2014).
liver cancer (continued). "In this review we summarize the crosstalk between EGFR and other signaling pathways that could be relevant to liver cancer development and treatment." (PMID 24212818, 2011). "In this article we review the crosstalk between the EGFR and other signaling pathways that could be relevant to liver cancer development and treatment." (PMID 24212818, 2011). "Silencing ST3GAL1 significantly reduced Siglec-7 ligand expression on liver cancer cells, enhancing their susceptibility to NK-mediated cytotoxicity and cetuximab-induced antibody-dependent cellular cytotoxicity (ADCC) in epidermal growth factor receptor (EGFR)-expressing tumor cells." (PMID 41961075, 2026). "EGF and its receptor (EGFR) may act as a bridge between inflammation and liver cancer." (PMID 40075616, 2025). "However, the EGFR signaling system also plays an important role in the development of liver cancer." (PMID 36077440, 2022). "In addition, we identified DDX20 as an essential gene for EGFR in the liver cancer cells." (PMID 36246406, 2022). "VEGFA and EGFR might be potential therapy targets of Xihuang pill in liver cancer." (PMID 32256653, 2020). "In conclusion, VEGFA and EGFR might be potential therapy targets of Xihuang pill in liver cancer." (PMID 32256653, 2020). "Thus, we speculated that genes such as VEGFA and EGFR might be potential therapy targets of Xihuang pill in liver cancer." (PMID 32256653, 2020). "ICC, an aggressive primary liver cancer with a low but clearly documented increase in incidence and mortality, is characterized by frequent over-expression of epidermal growth factor receptor (EGFR), vascular endothelial growth factor (VEGF), as well as other pro-angiogenic and hypoxia mediators." (PMID 26207380, 2015). "Cao found that The granule of the KXYA formula treated HBV-related liver cancer by regulating the expression of genes such as MAPK8, HDAC1, PTEN, NR3C1, EGFR and HNF4A." (PMID 39806972, 2025). "The combination of the EGFR inhibitor gefitinib and lenvatinib has strong anti-proliferative effects in xenografted liver cancer cells, immunocompetent animal models, patient-derived HCC tumors in mouse models, and liver cancer cell lines that express EGFR." (PMID 40556662, 2025). "The EGFR/FAK/AKT signaling pathway is effectively inhibited and finally plays a role in the treatment of liver cancer." (PMID 39806972, 2025). "Lu's research team found in the liver cancer cell line HepG2 that SOX2 increases the expression of EGFR, and EGFR upregulates miR-222-5p, leading to the downregulation of CYLD169." (PMID 40607251, 2025). "Consequently, inhibiting EGFR may be useful in treating hepatic cancer." (PMID 39502516, 2024). "Based on a PPI network, we ranked each protein by its degree value, and selected the top three core proteins EGFR and ESR1 for potential targets for liver cancer." (PMID 39457402, 2024). "In another study of liver cancer, researchers found that STEAP3 promotes cancer cell proliferation by facilitating nuclear transport of EGFR." (PMID 38440354, 2024). "The study identified AKT1, EGFR, ALB, and TNF genes as potential therapeutic targets against hepatic cancer." (PMID 39502516, 2024). "Further studies found that MNX1-AS1 can promote EGFR activation of PKM2 binding to importin α5, promote PKM2 nuclear translocation and increase liver cancer cell Warburg effect." (PMID 37861491, 2023).
liver cancer (continued). "Therefore, blocking EGFR genes might be beneficial to liver cancer treatment." (PMID 36817123, 2023). "Among all signaling pathways regulating liver cancer development and progression, we have focused on those elicited by the receptor tyrosine kinases (RTKs) MET and Epidermal growth factor receptor (EGFR), and TGF-β." (PMID 38138981, 2023). "The results indicated that the key targets of the pathway in cancer were related to the therapeutic effect of anti-liver cancer activities, including SRC, EGFR, ESR1, PTGS2, and APP." (PMID 36561345, 2022). "The results of molecular docking predicted that several key targets of liver cancer (along with MTOR, EGFR, MAPK3, and PIK3R1) bind stably with the corresponding active ingredient of F. indica." (PMID 35745580, 2022). "EGFR and MET are two molecules of the RTK family that were related to the survival time of liver cancer patients and resistance to targeted therapy in clinical reports." (PMID 35428350, 2022). "Comparing these findings with those provided by enrichment analysis four genes in particular, EGFR, MAPK3, MTOR, and PIK3R1, were identified as the main anti-liver cancer targets of F. indica and were chosen for molecular docking experiments." (PMID 35745580, 2022). "MiR-206 inhibits the expansion of liver cancer stem cells and HCC cell dedifferentiation by targeting the EGFR signaling pathway." (PMID 36233210, 2022). "Gene correlation between EGFR expression and genes associated with mAChRs in LIHC patients indicated there was a positive correlation (p < 0.05) between EGFR and CHRM2, CHRM3, CHRM4, and CHRM5 in liver cancer." (PMID 35565451, 2022). "Hence blocking the EGFR genes might help in the treatment of liver cancer." (PMID 35745580, 2022). "In current validated experiments, human liver cancer samples showed upregulated ESR1, EGFR mRNA expressions." (PMID 34592904, 2021). "In experimental verification, the clinical samples of liver cancer showed elevated ESR1, EGFR mRNA expressions." (PMID 34592904, 2021). "Meanwhile, we believe that miR-520b regulates liver cancer cell migration not only through MLKs but also by HBXIP, EGFR or the other target genes." (PMID 32214367, 2020). "Although previous study has confirmed the relation between EGFR expression and TCM active compounds using cell membrane chromatography, the effect of Xihuang pill on EGFR expression in liver cancer is still unclear." (PMID 32256653, 2020). "By binding to EGFR specifically, LNC-EGFR promotes Treg cell differentiation and promotes the immune escape of liver cancer cells." (PMID 33274204, 2020). "In a liver cancer pathway gene expression profile analysis of HepG2 cells transfected with C/EBPα-saRNA, EGF, EGFR, ADAM17 and β-catenin involved in EMT were down-regulated." (PMID 27050434, 2016). "It was demonstrated that by interacting with the EGFR/RAS/RAF pathway, sorafenib inhibits replication of Pexa-Vec in liver cancer, when applied in combination." (PMID 24822170, 2014). "It has been shown that blockage of EGFR and STAT3 cascades resulted in the inhibition of cancer cell proliferation and growth of prostate and liver cancer via cell cycle arrest and apoptosis." (PMID 18302761, 2008). "Likewise, DDX17 functions as a transcriptional regulator, driving the binding of the nuclear Y-box binding protein 1 (YB1) to the epidermal growth factor receptor (EGFR) gene and promoting its transcription, ultimately facilitating liver cancer metastasis." (PMID 38732173, 2024). "Nonetheless, in a paper by Jin and colleagues, the authors found no synergy in EGFRlow or EGFRhigh liver cancer cells between sorafenib and gefitinib (anti-EGFR)." (PMID 38338736, 2024). "Knockdown of integrin β1 could slow down liver cancer progression by inhibiting MET proto-oncogene, receptor tyrosine kinase (MET) and epidermal growth factor receptor signaling." (PMID 38374893, 2024).
liver cancer (continued). "Similarly, in liver cancer, Phosphatase of regenerating liver-3 (PRL-3) promotes MET via the activation of the epidermal growth factor receptor (EGFR) signaling pathway." (PMID 37006229, 2023). "CBG could reduce the expression of EGFR and CDK2 activity in human liver cancer cells, thereby inhibiting the growth of tumor cells, and enhancing the inhibitory effect of CBG on the proliferation potential of human liver cancer cells." (PMID 35011278, 2021). "As for the limitations of the current study, although the EGFR downstream effector RAS is a major proto-oncogene for human cancer, the RAS mutation is not very prevalent in patients with liver cancers, with 7% of patients having KRAS mutations and 4% of patients having HRAS mutations." (PMID 38791872, 2024). "Although EGFR inhibitors have not been approved for liver cancer, our finding may accelerate mechanism-based drug repurposing by incorporating EGFR_Y1068 as a patient stratification marker for clinical investigation." (PMID 38154692, 2023). "For example, EGFR and MET core fucosylation can potentiate their ligand binding ability and thus may enhance downstream signaling to support tumor growth and metastasis in liver cancer." (PMID 35303925, 2022). "Furthermore, our studies revealed that the EGFR, MAPK3, MTOR, and PIK3R1 genes are effective and potential therapeutic agents for lowering the incidence of liver cancer and potentially exhibiting therapeutic effects on liver cancer." (PMID 35745580, 2022). "Furthermore, we analyzed the active ingredient-target-pathway network and uncovered that Fumaridine, Lastourvilline, N-feruloyl tyramine, and Cryptopine conclusively contributed to the development of liver cancer by affecting the MTOR, MAPK3, PIK3R1, and EGFR gene." (PMID 35745580, 2022). "Thus, we speculated that the effect of Xihuang pill on liver cancer might be realized by targeting VEGFA and EGFR in pathways like proteoglycans in cancer and estrogen signaling." (PMID 32256653, 2020). "Furthermore, the effect of Xihuang pill on liver cancer might be realized by targeting VEGFA and EGFR in pathways like proteoglycans in cancer and estrogen signaling." (PMID 32256653, 2020). "Although the presence of Src mutants has not been described in liver cancer, c-Src activation is a common event in HCC and could participate in the sustained activation of EGFR pathway implicated in hepatocarcinogenesis." (PMID 24212818, 2011). "In our studies, we have suggested that locally elevated, aromatase-driven estrogen formation in human liver cancer tissues and cells may promote tumor cell growth through an estrogen-induced, ERα-mediated rise of AREG expression and the resulting activation of the EGFR signaling." (PMID 33925807, 2021). "A phase-II study of lapatinib, an inhibitor of EGFR and ERBB2, in patients with liver cancers revealed no response in CCA and a very low one in HCC (5%)." (PMID 27335842, 2014).